BCR (BCR activator of RhoGEF and GTPase)
Diseases named in the same sentence as BCR in open-access papers (continued):
Sharing a sentence is not in itself a finding about the gene and the disease.
acute lymphoblastic leukemia (continued). "Recently, various blood cell lineages expressing the BCR-ABL fusion gene in Philadelphia chromosome (Ph)-positive acute lymphoblastic leukemia (ALL) have been reported." (PMID 33194739, 2020). "Bilateral acute leukemic retinopathy, acute lymphoblastic leukemia (pro-B lymphocyte, BCR-ABL chimeric gene-positive)." (PMID 29443727, 2018). "The overexpression of INPP4B first became evident after the analysis of gene expression in leukemic blasts from BCR/ABL-positive pediatric acute lymphoblastic leukemia." (PMID 29343273, 2018). "TBC1D1 has been reported to have a potential downstream role of silencing of pre-BCR signaling in acute lymphoblastic leukemia in human." (PMID 29375555, 2017). "Here we report that in MYC-, RAS-, and BCR-ABL-induced acute lymphoblastic leukemia (ALL), apoptosis upon oncogene inactivation is mediated by the same pro-apoptotic protein, BIM." (PMID 27095570, 2016). "Treatment of Philadelphia chromosome (BCR-ABL translocation) - positive acute lymphoblastic leukaemia (birth to < 1 year)." (PMID 25091201, 2014). "A clinical follow-up was conducted on 137 B-ALL children with positive genes (59 cases of ETV6/RUNX1 positivity, 22 cases of E2A/PBX1 positivity, 25 cases of MLL positivity, and 19 cases of BCR/ABL positivity) among 302 children with acute lymphoblastic leukemia." (PMID 41195225, 2025). "A 31-year-old male presented with BCR:ABL1 positive acute lymphoid leukemia (Ph + ALL)." (PMID 37414968, 2024). "Furthermore, through this approach, BCR::ABL1 kinase activity was barely detectable in CP-CML compared to Ph+ acute lymphoblastic leukemia primary samples, where kinase activity is comparable to those measured in Ph+ cell lines." (PMID 35756686, 2022). "BCR, also known as BCR1, RhoGEF and GTPase activating protein, is a protein-coding gene, which has been associated with 8p11 myeloproliferative syndrome (EMS), chronic myeloid leukemia (CML), and acute lymphoblastic leukemia (ALL)." (PMID 31105873, 2019). "The ABL kinases were initially identified as oncogenes in the context of patients with chronic myelogenous leukemia (CML) and acute lymphocytic leukemia (ALL) who presented with BCR-ABL1 fusion proteins due to a chromosomal translocation of ABL1 to the Breakpoint Cluster Region (BCR) gene sequences." (PMID 30956771, 2019). "In addition, it has been shown that CDKN2A loss can contribute towards resistance to targeted therapy in acute lymphoblastic leukemia induced by BCR-ABL translocation." (PMID 21423728, 2011). "For treatment of BCR–ABL-positive acute lymphoblastic leukaemia or lymphatic blast crisis of CML, TBI-containing regimens are generally preferred due to the higher irradiation sensitivity of lymphoid blasts and due to the risk of relapse in the central nervous system." (PMID 11986785, 2002). "BCR::ABL1 oncogene is also present in 20–30% of acute lymphoblastic leukemia (Ph + ALL) cases, a rare aggressive lymphoid malignancy that predominantly involves B-lymphocytes." (PMID 39774950, 2025). "We next applied our targeting and data analysis strategy to a BCR::ABL1-positive B-cell precursor acute lymphoblastic leukemia (BCP-ALL) patient sample at first diagnosis." (PMID 41372142, 2025). "A 10-year-old boy with BCR/Abl-positive acute lymphoblastic leukemia (ALL) underwent hematopoietic stem cell transplantation (HSCT) from a partially HLA-matched donor." (PMID 40678133, 2025). "This real-life study compared mutation profiles and their impact on outcomes in 80 AYA, 97 adult, and 16 pediatric CML-CP patients, alongside 81 BCR::ABL1-positive acute lymphoblastic leukemia (Ph+ ALL) patients." (PMID 40295826, 2025). "Philadelphia chromosome-positive acute lymphoblastic leukemia (Ph+ ALL) is a genetically distinct and aggressive leukemia subtype with the presence of the BCR-ABL fusion gene." (PMID 40072099, 2025).
acute lymphoblastic leukemia (continued). "Z‐fusion genes are the most frequent fusion genes in Japanese adult BCR::ABL1‐negative B‐cell acute lymphoblastic leukemia (B‐ALL), while they are much less frequent in the US." (PMID 39015025, 2024). "The application of tyrosine kinase inhibitors and targeted immunotherapy has revolutionized the therapeutic strategies and clinical outcome for BCR::ABL1-positive B-cell acute lymphoblastic leukemia (BCR::ABL1+ B-ALL)." (PMID 39231779, 2024). "Philadelphia chromosome-positive B cell acute lymphoblastic leukemia (B-ALL), characterized by the BCR::ABL1 fusion gene, remains a poor prognosis cancer needing new therapeutic approaches." (PMID 38457494, 2024). "Acute lymphoblastic leukemia (ALL) is the most common childhood cancer and the presence of BCR::ABL1 fusion in p190 isoform is a marker for worse prognosis, associated with treatment resistance and reduced overall survival." (PMID 38067214, 2023). "For acute lymphoblastic leukemia (ALL), therapy with a tyrosine kinase inhibitor, such as Imatinib, is assumed to be highly beneficial in the presence of an BCR:ABL translocation." (PMID 36982036, 2023). "A typical example is the Philadelphia chromosome found in a subtype of acute lymphoblastic leukemia (Ph+ ALL) and chronic myeloid leukemia (CML), in which the BCR-ABL fusion gene encodes a protein with deregulated kinase activity." (PMID 37926284, 2023). "The same group evaluated the efficiency of CEL_Amide LIMKi in Philadelphia chromosome-positive (BCR::ABL+) acute lymphoblastic leukemia (ALL), another subtype of leukaemia." (PMID 36899941, 2023). "Philadelphia chromosome-positive (Ph+) acute lymphoblastic leukemia (ALL) expressing the chimeric tyrosine kinase BCR-ABL is one of the most common types of ALL in adults." (PMID 34117218, 2021). "Chronic myeloid leukemia (CML) and Ph+ acute lymphoblastic leukemia (ALL) are characterized by the presence of the BCR-ABL oncoprotein, which leads to activation of a plethora of mitogenic and pro-survival pathways, including the mTOR signaling cascade." (PMID 31546746, 2019). "The BCR-ABL fusion gene has also been reported less frequently in acute lymphoblastic leukemia (ALL) and rarely in AML." (PMID 28086240, 2017). "Aberrant pre-BCR signaling is considered as a key factor for B-cell precursor acute lymphoblastic leukemia (BCP-ALL) development." (PMID 27611867, 2016). "We have some knowledge of PP2A role in CML and Philadelphia chromosome positive acute lymphoblastic leukemia (Ph+ ALL) thanks in large part to the work of the Perrotti group in their studies on BCR–ABL regulation of PP2A in these diseases." (PMID 25750899, 2015). "Tyrosine kinase inhibitors (TKIs) have demonstrated success in the treatment of acute lymphoblastic leukemia (ALL) in patients that express BCR-ABL rearrangements (Philadelphia chromosome [Ph])." (PMID 25415187, 2014). "P210BCR-ABL is detected in more than 95% of cases with Ph+CML and one third of cases with Ph+ Acute Lymphoblastic Leukemia (Ph+ ALL).5 m-BCR involves intron 1 and joins exon 1 (e1) with a2 resulting in a smaller fusion transcript, e1a2." (PMID 25097530, 2014). "Dysregulation of Abl via fusion of the Abl gene to the BCR gene is the cause of chronic myelogenous leukemia (CML) and an aggressive subtype of acute lymphoblastic leukemia (ALL)." (PMID 19402756, 2009). "Subtypes of Acute Lymphoblastic Leukemia: This data set, available on the website, contains 6 subtypes of pediatric acute lymphoblastic leukemia, corresponding to six diagnostic groups: BCR-ABL, E2A-PBX1, MLL, T-ALL, TEL-AML1, Hyperdiloid>50." (PMID 16774678, 2006). "The historical standard of care for adults with newly diagnosed Philadelphia chromosome-positive (Ph+) acute lymphoblastic leukemia (ALL) was chemotherapy plus a BCR::ABL1 tyrosine kinase inhibitor (TKI), followed by allogeneic stem cell transplant (alloSCT) in first remission." (PMID 40369607, 2025).
acute lymphoblastic leukemia (continued). "Dasatinib (DAS), a multi-kinase inhibitor targeting Src and BCR-ABL families, is approved for Ph+ acute lymphoblastic leukemia (ALL) and chronic lymphocytic leukemia (CML)." (PMID 41049424, 2025). "BCR::ABL1 fusion is a genetic hallmark of chronic myeloid leukemia (CML) and is found in approximately 20%–50% of adult patients with acute lymphoblastic leukemia (ALL)." (PMID 38633128, 2024). "Traditionally, therapy for Philadelphia-positive acute lymphoblastic leukemia (Ph+ ALL) consists of BCR-ABL tyrosine kinase inhibitor (TKI) plus intensive multi-agent chemotherapy, which is associated with prolonged myelosuppression and life-threatening cytopenias." (PMID 39175510, 2024). "Of those 39 individuals with BCR::ABL1 gene fusion, 37 (95%) presented with acute lymphoid leukemia." (PMID 37686670, 2023). "In rare cases of CML and two-thirds of Ph-positive acute lymphoblastic leukemia (Ph+ ALL), the breakpoint occurs in the first intron on the BCR gene (m-BCR), creating the P190BCR-ABL1 from the e1a2 transcript." (PMID 34922630, 2021). "This is in contrast to the highly efficient effect of dasatinib in BCR-ABL-driven diseases such as chronic myeloid leukemia (CML) and Philadelphia-chromosome-positive acute lymphoblastic leukemia (Ph+ ALL), characterized by the constitutively active tyrosine kinase, BCR-ABL." (PMID 31040916, 2019). "TBC1D8 was found among differentially expressed genes in pre‐B acute lymphocytic leukemia samples with ALL1/AF4, E2A/PBX1, and BCR/ABL molecular rearrangements, and positively controls cell proliferation." (PMID 31254352, 2019). "For example, while the largest analysis of patents with acute lymphoblastic leukemia did not reveal an enrichment of A91V carriers compared to healthy controls, a subset of the ALL patients who also had BCR-ABL translocations were more likely to carry the A91V allele than the control group." (PMID 24376445, 2013). "Compared to several other learning algorithms, MDR gives the greatest AUC (area under the ROC curve) for the classifications of prostate cancer, acute lymphoblastic leukemia (ALL) and four ALL subtypes: BCR-ABL, E2A-PBX1, MALL and TALL." (PMID 18831787, 2008). "Philadelphia chromosome-positive (Ph-positive) acute lymphoblastic leukemia (ALL) is the most common subtype of ALL in adults, characterized by the abnormal formation of the Philadelphia chromosome, which leads to the development of the BCR::ABL1 gene with increased activity." (PMID 37798335, 2023). "Moreover, approximately 25–30% of acute lymphoblastic leukemia (ALL) cases exhibit the characteristic Philadelphia chromosome and positive BCR-ABL expression." (PMID 35672796, 2022). "Ponatinib (PON) is a third-generation BCR-ABL TKI approved by the United States Food and Drug Administration in December 2012 as the second-line treatment of CML and Philadelphia chromosome-positive acute lymphoblastic leukemia (ALL)." (PMID 36233014, 2022). "Activation of AMPK or conversely inhibition of mTOR appear therefore as pertinent therapeutic options for the treatment of BCR-ABL expressing malignancies raising the potential use of AMPK activators such as Aca or Metformin in the treatment of refractory CML and Ph(+) acute lymphoblastic leukemia." (PMID 31881723, 2019). "Furthermore, S1P inhibits classical apoptosis in T acute lymphoblastic leukemia (T-ALL) and SPHK1 level is increased in B-ALL, contributing to the development of murine BCR/ABL1 ALL." (PMID 29216917, 2017). "Dasatinib is an oral multi- BCR/ABL and Src family tyrosine kinase inhibitor, which is used to treat patients with chronic myelogenous leukemia (CML) or Philadelphia chromosome-positive acute lymphoblastic leukemia (Ph+ALL)." (PMID 26393679, 2015).
acute lymphoblastic leukemia (continued). "In the majority of cases (7 of 8 xenografts and the murine BCR-ABL model) we demonstrated equal efficacy of the two dexamethasone dosing regimens; whereas for one acute lymphoblastic leukemia sample, the discontinuous regimen yielded inferior antileukemic efficacy (log-rank p = 0.002)." (PMID 26252865, 2015). "The BCR/ABL oncogenic fusion protein is derived from translocation of the c-ABL gene on chromosome 9 to the BCR locus on chromosome 22 and is present in a large majority of CML cases, as well as in some acute lymphocytic leukemias." (PMID 26087188, 2015). "Dasatinib, which targets a variety of tyrosine kinases, most notably the BCR/ABL fusion protein and the Src Family Kinases (SFKs), is used for the treatment of BCR/ABL+ CML and acute lymphocytic leukemia with imatinib resistance or intolerance to previous therapy." (PMID 23825585, 2013). "Mutation of JAK2 is observed in several hematological disorders including ET, Polycythemia Vera, Primary Myelofibrosis and Acute Lymphoid Leukemia (ALL) as well as chromosomal translocations involving the fusion partners TEL, BCR, PCM1, PAX5, SEC 31A and SSBP2." (PMID 24086539, 2013). "BCR-Abl-targeting TKIs inhibit the activity of the BCR-Abl fusion protein, which is characteristic of chronic myeloid leukemia (CML) and Philadelphia chromosome-positive acute lymphoblastic leukemia (Ph+ ALL)." (PMID 41007845, 2025). "Analysis of IRF8 expression in GSE13425 showed that IRF8 expression levels were markedly lower in T‐ALL than in B‐cell acute lymphoblastic leukemia (B‐ALL) with cytogenetic subtypes such as TEL‐AML1, hyperdiploid, and BCR‐ABL." (PMID 36478193, 2023). "We investigated four PFG, namely: MLL-AF4, BCR-ABL p190, and AML1-ETO, MLL-AF9, which are characteristic for both acute lymphoblastic leukemia (ALL) and acute myeloid leukemia (AML), respectively." (PMID 37726322, 2023). "Positive (Ph+) acute lymphoblastic leukemia (ALL) and more than 95% of chronic myelogenous leukemia (CML) patients have the BCR-ABL fusion gene." (PMID 34249939, 2021). "Dasatinib is a dual BCR/ABL and Src family tyrosine kinase inhibitor approved for chronic myelogenous leukemia (CML) and acute lymphoblastic leukemia (ALL) treatment." (PMID 33467099, 2021). "Using RT-qPCR, we have screened for TEL-AML1 and BCR-ABL fusion genes, which are most abundant in acute lymphoblastic leukemia (ALL)." (PMID 31700008, 2019). "In acute lymphoblastic leukemia Philadelphia chromosome-positive (Ph + ALL), it was demonstrated that curcumin potentiated the efficiency of imatinib by inhibiting the activation of the AKT/mTOR signaling and by down-regulating the expression of the BCR/ABL gene." (PMID 30045750, 2018). "For example, acute lymphoblastic leukemia (ALL) is a heterogeneous disease, including several subtypes (T-ALL, E2A-PBX1, BCR-ABL, TEL-AML1, MLL) differing in their response to chemotherapy." (PMID 25347824, 2014). "In acute lymphoblastic leukemia (ALL), the most common malignancy of childhood, patients have long been known to have characteristic translocations including ETV6-RUNX1, TCF3-PBX1, BCR-ABL, and rearrangements of MLL with numerous partners." (PMID 23487523, 2012). "Pro-B cell childhood acute lymphoblastic leukemia (ALL) has event-free five year survival probabilities of 85–90% for the TEL-AML subtype and 20–40% for the BCR-ABL subtype." (PMID 16638124, 2006). "However, Dasatinib, an inhibitor of the constitutively active tyrosine kinase BCR-ABL, is already used for treating Philadelphia chromosome-positive acute lymphoblastic leukemia (Ph+ ALL) in cases of resistance or intolerance to prior therapies." (PMID 39372928, 2024). "BCR/ABL1 plays a key role in development of chronic myelogenous leukemia (CML) and in some cases of Philadelphia chromosome-positive acute lymphoblastic leukemia (Ph1-ALL)." (PMID 37165001, 2023).
acute lymphoblastic leukemia (continued). "Likewise, the presence of well-characterized fusion proteins in leukemia, notably the BCR-ABL fusion in chronic myelogenous leukemia and acute lymphoid leukemia, enabled the demonstration that circulating T cells could recognize neo-epitopes created by the fusion." (PMID 32153583, 2020). "Philadelphia chromosome‐like acute lymphoblastic leukaemia (Ph‐like ALL), also known as BCR::ABL1‐like ALL, is characterized by a gene expression profile resembling that of ph + ALL but lacking the typical BCR::ABL1 fusion gene." (PMID 38323741, 2024). "Dasatinib is an oral multi-BCR/ABL and Src family tyrosine kinase inhibitor approved for the use in patients with chronic myelogenous leukemia (CML) after imatinib treatment and in patients with Philadelphia chromosome-positive acute lymphoblastic leukemia (Ph+ALL)." (PMID 25193862, 2014).